TNF (tumor necrosis factor)
Diseases named in the same sentence as TNF in open-access papers (continued):
Sharing a sentence is not in itself a finding about the gene and the disease.
nephrotic syndrome (23 papers, 2011 to 2025). A collection of symptoms that include severe edema, proteinuria, and hypoalbuminemia; it is indicative of renal dysfunction. "The primary goal of the meta-analysis was to investigate the relationship between Nephrotic Syndrome and the TNFα 308 G/A [rs1800629] polymorphism of the cytokine gene." (PMID 40813446, 2025). "This research marks a initiative to explore the potential impact of TNF-α promoter gene polymorphisms, specifically the − 308 G/A variant and its related haplotype, on susceptibility to Nephrotic Syndrome." (PMID 40813446, 2025). "In this study, emphasis has been placed on TNF-α as a crucial contributor to the development and progression of diverse inflammatory conditions linked to proteinuria in Nephrotic Syndrome." (PMID 40813446, 2025). "This meta-analysis, which included 1,560 participants (628 cases and 932 controls), shows a strong correlation between the TNFα -308 G/A (rs1800629) polymorphism and the risk of developing childhood nephrotic syndrome." (PMID 40813446, 2025). "Many previous studies have examine the connection between TNFα 308 G/A polymorphisms and childhood Nephrotic syndrome in various populations." (PMID 40813446, 2025). "Case Report: A 56-year-old male with a long-standing history of CD treated with a tumor necrosis factor-α inhibitor presented with an acute elevation of creatinine in association with clinical and laboratory markers of nephrotic syndrome." (PMID 34566512, 2021). "Collectively, our study reinforces the hypothesis that the A allele in the TNF-α − 308 polymorphism plays a contributory role in the development of childhood Nephrotic Syndrome, likely through enhanced cytokine expression and immune activation." (PMID 40813446, 2025). "Hence, the indispensability of this meta-analysis is to validate the correlation between the TNFα 308 G/A [rs1800629] genetic polymorphism in the cytokine gene and Nephrotic Syndrome in children." (PMID 40813446, 2025). "It has long been suggested that TNF-α is one of the circulatory permeability factors involved in the pathogenesis of nephrotic syndrome." (PMID 38610653, 2024). "Nephrotic syndrome is consistently associated with elevated levels of serum IL-2, IL-2R, IFN-γ, and TNF-α and normal levels of IL-1α, IL-1β, and IFN-α." (PMID 38127456, 2024). "The results showed that the serum levels of cholesterol, triglyceride, TNF-α, and IL-6 in rats with nephrotic syndrome were increased and the gene and protein expressions of AQP2 and AVP were up-regulated in rats with adriamycin injected into caudal vein." (PMID 36678585, 2023). "The possible mechanisms are monocytosis, increased serum and urine lysozyme levels and tumor necrosis factor-alpha (TNF-α) in MDS patients related to nephrotic syndrome or interstitial nephritis." (PMID 32968161, 2020). "In Pedigo’s report, 6 patients with FSGS and 14 patients with steroid-dependent nephrotic syndrome were found to have levels of serum TNFα comparable to healthy controls." (PMID 31095586, 2019). "Elevated levels of serum TNF have been described in patients with nephrotic syndrome and a beneficial role of TNF inhibition was observed in a subset of pediatric patients with FSGS." (PMID 31581251, 2019). "Levels of inflammatory cytokines, such as tumor necrosis factor α and interleukin-8, are often increased in nephrotic syndrome including FSGS, and eliminating such humoral factors by LDL apheresis can decrease proteinuria." (PMID 29808114, 2018). "Glomeruli isolated from mice with nephrotic syndrome also had increased expression of IL-1β and TNF RNA." (PMID 23382978, 2013). "Previous studies have shown that the expressions of Proinflammatory cytokines, IL-6 and TNF-α, both increase in nephrotic syndrome." (PMID 21822358, 2011). "Increased TNF-α levels have been observed in plasma and urine of Nephrotic Syndrome patients." (PMID 40813446, 2025).
nephrotic syndrome (continued). "Exposing cultured mouse podocytes for 24 h to recombinant TNFα, a circulating factor implicated in pediatric nephrotic syndromes, did not affect the total abundance of KCa1.1, but did evoke significant increases in both β4 and γ3." (PMID 39791723, 2024). "Elevation of TNF-α has been found in the plasma and urine of patients with nephrotic syndrome." (PMID 29549463, 2019). "Immune system derangements resulting in an inflammatory state have been described during proteinuria in nephrotic syndrome and include a few mediators of inflammation, like IL17 A, TNF-α, IFN-γ, TLR-3, and CRP." (PMID 33585371, 2020). "Moreover, the combination of TNF-α and IFN-γ in the induction of podocytes can mimic steroid resistant nephrotic syndrome in vitro." (PMID 36866869, 2023). "It has been suggested that tumor necrosis factor alpha (TNFα) and CD95 may play an important role in the pathogenesis of nephrotic syndrome." (PMID 25126087, 2014). "TNFα and CD95 were found significantly increased in patients with nephrotic syndrome." (PMID 25126087, 2014). "Collectively, these observations raise the possibility that the TNFα signaling pathway may be involved in the pathogenesis of nephrotic syndrome in some (but not all) idiopathic SRNS/FSGS patients." (PMID 31095586, 2019).
pneumococcal pneumonia (23 papers, 2008 to 2024). A febrile disease caused by STREPTOCOCCUS PNEUMONIAE. "Elevated TNF-α is known to impair immune cell function in aged hosts and contribute the enhanced susceptibility to pneumococcal pneumonia, and several aspects of immune impairment and pulmonary pathology seen in aging can be recapitulated by administration of TNF-α to young hosts." (PMID 38828722, 2024). "TNFα is an effective inducer of inflammatory responses and is important during pneumococcal pneumonia for the host defense mechanism." (PMID 38234660, 2024). "We also assessed BALF levels of other important pro-inflammatory mediators during pneumococcal pneumonia such as TNF-α, IL-6 and CCL2." (PMID 37275853, 2023). "During pneumococcal pneumonia in mice, high levels of IL-6, IL-1β and TNF-α are produced in the early stages of lung parenchyma and/or bronchoalveolar space infection." (PMID 34925324, 2021). "Experiments in mice have shown that MIP-1α, KC and TNFα level in BAL fluid dramatically increase in the acute phase of pneumococcal pneumonia." (PMID 32481512, 2020). "Since cytokines are important regulators of the host immune response during pneumococcal pneumonia we measured levels of the following cytokines in lung homogenates and plasma: TNF-α, IL-6, IL-10, IL-12p70, IFN-γ, MCP-1 and KC." (PMID 25366058, 2014). "Serotype 11a (M10) murine pneumococcal pneumonia resulted in an early local levels of TNF-α and IL-6 in the pulmonary compartment, whereas serotype 3 (ATCC6303) displayed a more delayed response, which remained until death occurred." (PMID 21483672, 2011). "TNFα represents another important cytokine induced in pneumococcal pneumonia." (PMID 30100903, 2018). "Consistent with this, it has been reported that treatment with neutralizing anti-TNF monoclonal antibody resulted in an enhanced outgrowth of S. pneumoniae in the lungs and blood, along with significantly earlier death in mice with pneumococcal pneumonia as compared with control mice." (PMID 29922273, 2018). "Indeed, sustained high levels of TNF-α, IL-6 and IFN-γ are associated with increased disease severity during pneumococcal pneumonia." (PMID 27973447, 2016). "Thus, in line with our in vitro findings, in vivo expression of KLF4 in myeloid cells increases the release of the pro-inflammatory cytokines TNF-α, KC and IL-1β and decreases the release of the anti-inflammatory cytokine IL-10 in murine pneumococcal pneumonia." (PMID 34589087, 2021). "However, it is unlikely that the amelioration of acute inflammatory reponses in the lung by ibrutinib resulted solely from reduced TNF production, since we previously found that anti-TNF therapy impaired bacterial clearance during ceftriaxone-treated pneumococcal pneumonia and aggravated pathology." (PMID 30646846, 2019). "Furthermore, during pneumococcal pneumonia TNF-α could compensate for the attenuated host defense response in type I IL-1 receptor-deficient mice." (PMID 26973817, 2016). "Considering that especially low TNF-α concentrations in the lungs early after induction of pneumococcal pneumonia are important for limiting the growth of S. pneumoniae, this differential response may have contributed to the enhanced growth of S. pneumoniae PLN in TLR2 KO mice." (PMID 17711480, 2008).
retinal ischemia (23 papers, 2010 to 2025). A ischemic disease that involves the retina. "Among these small molecules, tumor necrosis factor-alpha (TNF-α) has been identified as an effective molecule that enhances the therapeutic effects of MSC-EV on retinal ischemia-reperfusion injury, periodontal bone loss, and wound healing." (PMID 40755851, 2025). "Significantly increased serum levels of TNF-α protein and associated retinal ischemia were found in Eales’ disease which is an idiopathic inflammatory retinal vasculopathy." (PMID 35576057, 2022). "TNF-α-stimulated gingival MSC-derived EV demonstrated enhanced neuroprotective effects in a retinal ischemia-reperfusion injury model, which was attributed to the enrichment of miR-21–5p." (PMID 40755851, 2025). "Retinal ischemia increases compensatory angiogenesis, tissue remodeling and inflammation, presumably mediated by elevated expression of IL-6, IL-1β, TNFα and VEGF." (PMID 36983353, 2023). "Similar results have been reported regarding MΦs, as it was shown that caffeine decreased TNF-α secretion from Kupffer cells isolated from ethanol-fed mice, and in microglia following retinal ischemia-reperfusion." (PMID 34371919, 2021). "MIP-1β, TNF-α and IL-18 are proinflammatory factors that can compromise the blood–retinal barrier, exacerbate retinal ischemia, modulate angiogenesis, and induce the progression of ROP." (PMID 32728160, 2020). "Increased levels of TNF-α were observed in the early stage of retinal ischemia and in several neurodegenerative diseases, and TNF-α was proposed as a pivotal cytokine mediating neuron death." (PMID 23691186, 2013). "Additionally, intracellular adhesion molecules, along with endothelial and glial cells, induce the upregulation of VEGF, TNF-α, IL-6, and IL-1β, leading to retinal ischemia and hypoxia." (PMID 39634174, 2024). "These genes are pro-inflammatory factors downstream of TNFα and NF-κB signaling, and could potentially be effective therapeutic targets for inflammation secondary to retinal ischemia." (PMID 32735610, 2020). "Etanercept is a commercially available TNF-α inhibitor, and the present study confirmed its efficacy in terms of preserving axonal structure and decreasing microglial activation in a rat model of retinal ischemia." (PMID 27259948, 2016). "Retinal ischemia results in increased expression of TNF-α and its receptors (TNF-R1 and TNF-R2)." (PMID 21152396, 2010). "However, it may have an adverse role in retina as TNF-alpha blockers suppressed retinal damage in a retinal ischemia model." (PMID 27527066, 2016). "In rats subject to retinal ischemia-reperfusion, NaMESys-SOR significantly inhibited retinal expression of tumor necrosis factor-alpha (TNFα, 20.7%) and inducible nitric oxide synthase (iNos, 87.3%) mRNAs in comparison to controls." (PMID 33922399, 2021). "Tumor necrosis factor-α (TNF-α), interleukin-6 (IL-6), and adhesion molecules ICAM-1 and VCAM-1 were observed in patients with retinal ischemia." (PMID 28273868, 2017). "Retinal ischemia-reperfusion resulted in elevated levels of TNF-α protein in the vitreous and TNF-α mRNA in the neuroretina; the expression of TNF-R1 and TNF-R2 mRNA was also increased in both the neuroretina and retinal arteries." (PMID 21152396, 2010). "Additionally, microglia have been identified as the primary source of proinflammatory cytokines, such as TNF-α, which mediates RGC death through its receptor TNF-R1 in both TON and retinal ischemia." (PMID 39769388, 2024). "However, TNF-transgenic mice are protected against glutamate excitoxicity mainly by up-regulation of TNFR2 signaling as shown in vitro and in a retinal ischemia model and high TNF levels more likely employ TNFR2 signaling." (PMID 22848506, 2012). "Retinal ischemia induces the expression of monocyte chemoattractant protein-1 (MCP-1) and macrophage inflammatory protein-1α (MCP-1α) to recruit and activate circulating macrophages, which in turn activate microglial macrophages to release tumor necrosis factor (TNF-α)." (PMID 38985778, 2024).
retinal ischemia (continued). "Tumor necrosis factor alpha (TNF-alpha) is a cytokine produced and released by activated microglia that regulates the expression of neurotrophins and their receptors in glial cells and monocytes, modulates neurite outgrowth, and acts as a neuroprotective agent in models of retinal ischemia." (PMID 32455921, 2020).
viral pneumonia (23 papers, 2013 to 2026). Inflammation of the lung parenchyma that is caused by a viral infection. "Treatment of respiratory syncytial virus pneumonia mainly through TNF signaling pathway and IL-17 signaling pathway." (PMID 39889188, 2025). "In patients with viral pneumonia, positive correlations were found between TNF-α and Fusobacterium nucleatum (p = 0.005), while IL-2 positively correlated with Capnocytophaga granulosa (p = 0.011)." (PMID 41011430, 2025). "In human medicine, certain cytokines such as IL-8, TNF-α, and IL-10 have recently been used to differentiate Mycoplasma pneumoniae infection from viral pneumonia in children." (PMID 40703922, 2025). "This study was performed to demonstrate the effects of methylprednisolone (MPS) and azithromycin treatment on serum biochemical factors and their impact on Serum Biochemical Factors (CRP, PCT, IL-6, TNF-a) prognosis in patients with viral pneumonia (VP)." (PMID 40821637, 2025). "Previous studies have reported that XCHG relieves fever and improves viral pneumonia by inhibiting pro-inflammatory cytokines (IL-1β, IL-6, and tumor necrosis factor [TNF]-α)." (PMID 38675434, 2024). "As an early cytokine of viral pneumonia, the expression of TNF-α can regulate other proinflammatory factors downstream." (PMID 35145559, 2022). "Additionally, it has been shown that electroacupuncture at BL13 down-regulates the lung index and serum TNF-α levels and up-regulates serum IL-10 levels in mice with viral pneumonia." (PMID 40098935, 2025). "ELISA results showed that XCH treatment could decrease levels of BALF IL-6, IL-1β, and TNF-α in mice with viral pneumonia." (PMID 35865338, 2022). "In cerebral and pulmonary tissues, the P9 virus replication induced the production of G-CSF, IFN-γ, IL-6, CXCL1, MCP-1, MIP-1α, RANTES, IP-10, MIP-1β, and TNF-α, as well as pathological alterations including reduction of neuronal cells and typical symptoms of viral pneumonia." (PMID 35755996, 2022). "Additionally, serum inflammatory cytokine levels, such as IL-1β, TNF-α, and GM-CSF, were higher in these patients than in healthy volunteers, suggesting that significant inflammation was observed in patients with viral pneumonia." (PMID 40659620, 2025). "Moreover, EA extract inhibits the overproduction of inflammatory cytokines, including IL-6, TNF-α and MCP-1, in mice induced by viral pneumonia." (PMID 36431955, 2022). "Severe viral pneumonia was observed in the infected mice on Day 4 post-infection, which showed that H1N1 virus infection triggered alveolar tissue destruction (P < 0.01), pulmonary edema, and hemorrhage (P < 0.01), accompanied by high levels of the inflammatory cytokine TNF-α (P < 0.01)." (PMID 35371077, 2022). "However, TNF-α may not play a significant antiviral role, and its levels in serum do not change significantly during viral pneumonia." (PMID 30275916, 2018).
dermatomyositis (22 papers, 2005 to 2025). Dermatomyositis (DM) is a type of idiopathic inflammatory myopathy characterized by evocative skin lesions and symmetrical proximal muscle weakness. "Additionally, drug-induced dermatomyositis frequent occurrence was most commonly associated with medications such as Hydroxyurea, immune checkpoint inhibitors, statins, Penicillamine, and TNF inhibitors." (PMID 41293157, 2025). "Some surveys had inspected the effects of the tumor necrosis factor-α (TNF-α)-308A/G polymorphism on susceptibility to dermatomyositis (DM), and showed mixed results." (PMID 25101759, 2014). "The report of increased tumor necrosis factor (TNF) levels in dermatomyositis and polymyositis has led to the trial of the TNF blocking agents etanercept and infliximab in both conditions." (PMID 33530460, 2021). "These might indicate a post-transcriptional regulation of TNFα in dermatomyositis, alterations in protein degradation by the ubiquitin system, or other unknown mechanisms." (PMID 37250649, 2023). "In contrast, biologic-naïve IBD patients having dermatomyositis might benefit from TNF-α blockers." (PMID 33802483, 2021). "We performed a systematic search of databases from 1990 to 2013 to identify articles concerning the new onset of dermatomyositis/polymyositis (DM/PM) in patients treated with anti-TNF-α therapy." (PMID 24600322, 2014). "Reports of TNF-α blockade as a treatment for IIMs have not panned out at this time and new cases of dermatomyositis/polymyositis have been reported after administration of TNF-α therapy." (PMID 28524083, 2017). "In addition to its secretion by TNFα, TARS is the target of the PL-7 auto-antibody in polymyositis and dermatomyositis autoimmune disorders." (PMID 25535072, 2014). "In support of this, interferon gamma and tumor necrosis factor alpha, which are increased in IIM, can induce secretion of the CXCR3 ligand CXCL10 by muscle fibers, and CXCR3+ T cells have been identified in the muscle biopsies of polymyositis, dermatomyositis, and inclusion body myositis patients." (PMID 35371068, 2022). "Several studies have reported that TNFα is substantially increased within skin lesions of patients with discoid lupus erythematosus (DLE), subacute cutaneous lupus erythematosus (SCLE) and dermatomyositis (DM) compared to controls." (PMID 22217359, 2012).